TP53INP1 (tumor protein p53 inducible nuclear protein 1)
Description:
Antiproliferative and proapoptotic protein involved in cell stress response which acts as a dual regulator of transcription and autophagy. Acts as a positive regulator of autophagy. In response to cellular stress or activation of autophagy, relocates to autophagosomes where it interacts with autophagosome-associated proteins GABARAP, GABARAPL1/L2, MAP1LC3A/B/C and regulates autophagy. Acts as a tumor suppressor by inducing cell death by an autophagy and caspase-dependent mechanism. Can reduce cell migration by regulating the expression of SPARC.
Synonyms: p53DINP1; SIP; DKFZp434M1317; FLJ22139; TP53INP1A; TP53INP1B; Teap; TP53DINP1
Tractability: No criterion of Open Targets' tractability assessment is met for any kind of drug.
Gene: Protein-coding gene on chromosome 8 (94,925,972 to 94,949,395, reverse strand). Ensembl gene ENSG00000164938.
Subcellular location: Cytoplasm, cytosol; Nucleus; Nucleus, PML body; Cytoplasmic vesicle, autophagosome
Subcellular location (Human Protein Atlas): Cytosol
Gene Ontology:
Molecular function: protein binding; antioxidant activity
Biological process: autophagic cell death; positive regulation of autophagy; positive regulation of DNA-templated transcription; autophagosome assembly; negative regulation of cell migration; negative regulation of cell population proliferation; regulation of cell cycle; cellular oxidant detoxification; negative regulation of fibroblast proliferation; negative regulation of gene expression; negative regulation of myofibroblast differentiation; positive regulation of gene expression
Cellular component: autophagosome; cytosol; nucleus; nucleoplasm; PML body
Genetic constraint (gnomAD): Loss-of-function variants: 11 observed, 20.2 expected, observed/expected ratio (o/e) 0.54, 90% interval 0.34 to 0.9. The upper end of that interval is the gene's LOEUF score, 0.9, which puts it in group 3 of 6, group 1 being the genes least tolerant of losing a copy. Missense variants: 269 observed, 302.14 expected, observed/expected ratio (o/e) 0.89, 90% interval 0.81 to 0.99. Synonymous variants: 90 observed, 98.42 expected, observed/expected ratio (o/e) 0.91, 90% interval 0.77 to 1.09.
Homologues: Orthologues: chimpanzee TP53INP1 (99% identical), macaque TP53INP1 (98% identical), pig TP53INP1 (90% identical), guinea pig TP53INP1 (90% identical), dog TP53INP1 (88% identical), mouse Trp53inp1 (87% identical), rabbit TP53INP1 (87% identical), rat Trp53inp1 (86% identical), tropical clawed frog tp53inp1 (52% identical), zebrafish tp53inp1 (47% identical). Paralogues in human: TP53INP2 (28% identical).
Diseases named in the same sentence as TP53INP1 in open-access papers:
TP53INP1 is named in the same sentence as 79 diseases in open-access papers, as found by Europe PMC text mining. Sharing a sentence is not in itself a finding about the gene and the disease. The quoted sentences say what the papers report.
breast carcinoma (30 papers, 2011 to 2025). "Loss of TP53INP1 expression in breast cancer cells is due to oncogenic factors, such as miR-569, which suppress TP53INP1 expression through posttranscriptional mechanisms." (PMID 32448269, 2020). "Low mRNA levels of TP53INP1 were associated with a high histological grade of breast cancer (Table." (PMID 32448269, 2020). "In addition, the expression of VE‐cadherin, a hallmark of VM, was reduced in TP53INP1‐overexpressing breast cancer cells." (PMID 29655255, 2018). "TP53INP1 expression is often silenced in breast cancer cells and other human cancers, demonstrating that TP53INP1 is an unfavorable prognostic marker." (PMID 32448269, 2020). "An association between the MSI2a and TP53INP1 mRNA levels was also observed in our cohorts of breast cancer tissues, the CCLE breast cancer cell lines, TCGA breast cancer dataset, and the GESA76250 TNBC samples." (PMID 32448269, 2020). "By antagonizing TP53INP1 and Yes1 associated transcriptional regulator (YAP1), upregulated miR-200a enhances drug resistance in breast cancer." (PMID 33117693, 2020). "Next, we found that TP53INP1‐overexpressing breast cancer cells formed very few tube‐like structures in the hypoxic environment, whereas the control group formed more VM channels." (PMID 29655255, 2018). "High TP53INP1 expression was found in 64 of 100 breast cancer sample tissues (64%), and low expression was identified in 36 of 100 (36%) samples." (PMID 29655255, 2018). "First, we selected two of five spontaneous TA2 breast cancers; the TP53INP1 expression in these lines showed obvious differences by Western blotting." (PMID 29655255, 2018). "We showed that miR-200a promotes DNA damage resistance by inhibiting DNA damage-induced apoptosis via YAP1 and TP53INP1 in breast cancer." (PMID 29329575, 2018). "In conclusion, we identified a novel function of TP53INP1 that is associated with EMT and VM formation in breast cancer." (PMID 29655255, 2018). "In general, these results indicated that TP53INP1 not only attenuates breast cancer cell migration and invasion but also inhibits EMT, which suggests that TP53INP1 is related to VM formation." (PMID 29655255, 2018). "We found that 73 of 100 breast cancer samples had accompanying pericarcinous tissues; of these, the high expression of TP53INP1 was 49.3% (36/73) in breast cancer tissues and 65.8% (48/73) in matched adjacent tissues." (PMID 29655255, 2018). "Together with the in vitro experiments, we conclude that TP53INP1 inhibits breast cancer EMT and VM formation in vivo." (PMID 29655255, 2018). "Remarkably, TP53INP1 expression is inversely correlated with miR-200a expression in Breast cancer cell lines." (PMID 29329575, 2018). "To further evaluate the influence of TP53INP1 on hypoxia‐induced VM formation in breast cancer, we again assessed migration and invasion." (PMID 29655255, 2018). "To investigate TP53INP1 expression in human breast cancer tissues, we analysed 100 breast cancer samples by immunohistochemistry." (PMID 29655255, 2018). "To further clarify the relationship between TP53INP1 and VM formation in breast cancer, we explored the effect of TP53INP1 plasmid infection in vivo." (PMID 29655255, 2018). "Both Cebpa and Tp53inp1 can be down-regulated in breast cancer, and although validation also suggested a different effect of those diets in their expression, evident differences were not obtained." (PMID 26091908, 2016). "miR-155 is known to target genes such as SOCS1 and TP53INP1 enhancing proliferation in breast cancer cell lines." (PMID 25352952, 2014).
breast carcinoma (continued). "Taken together, these findings showed that TP53INP1 is a direct target of miR-155 in breast cancer cells and mRNA degradation is involved in miR-155-suppressing TP53INP1." (PMID 24152184, 2013). "TP53INP1 expression was investigated immunohistochemically in 81 cases of breast carcinoma, compared with normal breast tissue, decreased TP53INP1 expression was found in 45 cases (55.6%)." (PMID 24152184, 2013). "In summary, our researches suggest that miR-155 functions as an oncomiR by targeting TP53INP1 and contributes to the control of cell survival and growth in breast cancer cells." (PMID 24152184, 2013). "further evaluated the possibility that miR-155-5p therapy could contribute paclitaxel-resistance through the suppression of TP53INP1 in paclitaxel-resistant breast cancer cells." (PMID 40699776, 2025). "TP53INP1 has been implicated as a tumour suppressor in additional malignancies such as hepatocellular carcinoma (HPCC), breast cancer and pancreatic cancer, possibly providing scope for studying whether and how miR-155-5p/3p promote cancer in these contexts." (PMID 35611569, 2022). "Furthermore, breast cancer with low mRNA expression levels of both MSI2a and TP53INP1 correlated with the worst OS (p = 0.002)." (PMID 32448269, 2020). "In liver cancer cells, transforming growth factor beta 1 (TGF-β1) indirectly promotes epithelial-mesenchymal transition (EMT) and CSC phenotypes through down-regulation of TP53INP1 by miR-155 while in breast cancer, miR-155 is involved in tumor initiation via transcriptional repression of BRCA1." (PMID 31137686, 2019). "In addition, we also observed a correlation of TP53INP1 expression with the expression of HIF1‐α in breast cancer by Pearson analysis (r = −.0293, P = .003)." (PMID 29655255, 2018). "Thus, TP53INP1 expression was lower in breast cancer tissues than in pericarcinous tissues (P = .045)." (PMID 29655255, 2018). "Therefore, TP53INP1 can be reasonably assumed to suppress hypoxia‐induced breast cancer EMT and VM formation via the GSK‐3β/Snail pathway." (PMID 29655255, 2018). "We sought to determine whether TP53INP1 overexpression would be sufficient to inhibit EMT in breast cancer cells." (PMID 29655255, 2018). "Over-expression of TP53INP1 has been reported in breast cancer as a potential prognostic marker." (PMID 27876019, 2016). "Moreover, recent findings have shown a significant reduction of the expression of TP53INP1 during the development of breast cancer, stomach cancer, and pancreas cancer." (PMID 24152184, 2013). "Additionally, miR-155 can promote tumor invasion and metastasis in breast cancer by downregulating its target, RhoA and promote tumor invasion and metastasis in pancreas duct carcinoma by repressing the expression of TP53INP1." (PMID 21533124, 2011). "Low levels of TP53INP1 have been observed in breast carcinoma as compared to normal breast tissue." (PMID 22102859, 2011). "However, the molecular mechanism of the relationship between TP53INP1 and breast cancer VM formation is unknown." (PMID 29655255, 2018). "Therefore, we determined that whether overexpression of miR-155 led to down-regulation of TP53INP1 expression in human breast cancer cells." (PMID 24152184, 2013). "Our study here was to investigate the effects of miR-155 on cell proliferation, cell cycle and cell apoptosis of ERalpha (+) breast cancer cells and to verify whether TP53INP1 is a target of miR-155, and tried to explore the mechanisms of miR-155 in this process." (PMID 24152184, 2013). "Furthermore, decreased expression of TP53INP1 is involved in breast cancer progression." (PMID 22051041, 2011). "TP53INP1 suppresses gemcitabine resistance in pancreatic cancer, sorafenib resistance and DDP resistance in liver cancer, paclitaxel resistance in breast cancer, DDP resistance in lung cancer, etc.." (PMID 37993867, 2023).
breast carcinoma (continued). "Primarily, miR-155-3p acts as an oncogene via the direct inhibition of tumour suppressors such as TP53INP1 (adenocarcinoma), FBXW7 (hepatocellular carcinoma), PCDH7/CREB3/SIX1 (glioma), WDR82 (colorectal cancer) and CADM1 (breast cancer)." (PMID 35611569, 2022). "Treatment of MCF-7 breast cancer cells with these compounds lowered the expression of regulators of apoptosis TP53INP1 and APAF1 (but after 48 h of incubation with o,p′-DDT, the TP53INP1 amount increased)." (PMID 35051067, 2022). "TP53INP1 expression was significantly downregulated in 81.48% (22/27) of TNBC tissues vs. ANTs and other breast cancer subtypes in TCGA dataset." (PMID 32448269, 2020). "Specifically, TP53INP1 expression in TNBC was downregulated compared with that in normal tissues and other breast cancer subtypes." (PMID 32448269, 2020). "In our study, we investigated the role of TP53INP1 in breast cancer cells (BCC) EMT and VM formation under hypoxic conditions and preliminarily explored the ROS/Snail signalling pathway in TP53INP1‐mediated VM formation." (PMID 29655255, 2018). "Thus, TP53INP1 may be a key molecule involved in the breast cancer EMT process." (PMID 29655255, 2018). "Upregulated miR-200a enhances treatment resistance via antagonizing TP53INP1 and YAP1 in breast cancer." (PMID 29329575, 2018). "Together, our results show that TP53INP1 inhibits hypoxia‐induced EMT and VM formation via the ROS/GSK‐3β/Snail pathway in breast cancer, which offers new insights into breast cancer clinical therapy." (PMID 29655255, 2018). "TP53INP1 overexpression inhibited breast cancer invasion, migration, epithelial‐mesenchymal transition (EMT) and VM formation; conversely, TP53INP1 down‐regulation promoted these processes in vitro by functional experiments and Western blot analysis." (PMID 29655255, 2018). "Surprisingly, the two cancer cell line controls, the colorectal HCT-15 and the breast cancer MCF-7, also expressed TP53INP1 to different levels." (PMID 28962647, 2017). "Through genomic approaches in MCF7-ADR; a drug-resistant breast cancer cell line, our results reflect the unique features of drug-resistance, including MDR1 overexpression via genomic amplification and miRNA-mediated TP53INP1 down-regulation." (PMID 22051041, 2011). "Indeed, the features of a drug-resistant breast cancer cell line were assessed by genomic approaches and MDR1 overexpression, together with miRNA-mediated TP53INP1 down-regulation, were found." (PMID 31947507, 2020). "Statistical analysis showed that VE‐cadherin was highly expressed in 26 of 36 (72.2%) TP53INP1‐negative breast cancer tissues (P = .044), and there was a negative correlation between TP53INP1 and VE‐cadherin (Pearson analysis r = −.0227, P = .023)." (PMID 29655255, 2018). "TP53INP1 inhibits hypoxia‐induced EMT and VM formation via the ROS/GSK‐3β/Snail pathway in breast cancer, especially in triple‐negative breast cancer." (PMID 29655255, 2018).
pancreatic cancer (26 papers, 2008 to 2024). "In the pancreatic TME, CAF-Exo miR-106b was found to directly reduce tumor protein 53-induced nuclear protein 1 (TP53INP1) expression, which in turn increased gemcitabine resistance in pancreatic cancer cells." (PMID 39187523, 2024). "The downregulation of TP53INP1 induced by MV-enclosed miR-155 from pancreatic cancer cells mediates the proliferation and activation of normal fibroblasts, and also manifests CAF characteristics." (PMID 35501802, 2022). "TP53INP1 expression is repressed by miR-155 in pancreatic cancer, and its restoration inhibits pancreatic tumor development." (PMID 35501802, 2022). "Pancreatic cancer-derived EVs carrying miRNA-106b directly targeted TP53INP1, promoting gemcitabine resistance." (PMID 34943937, 2021). "In this network, many intersections have been verified in experiments; for example, miR-155 was upregulated, blocking the translation of TP53INP1 to induce cell migration during pancreatic cancer evolution." (PMID 34386492, 2021). "Overexpression of SPARC also mediated the suppressing effect of TP53INP1 on the migration of pancreatic cancer cells and promoted the progression of malignant cancers." (PMID 33195283, 2020). "A previous study claimed that miR-155-5p mediated pancreatic cancer derived microvesicles reprogramming normal adjacent fibroblasts into CAF by downregulation of TP53INP1 protein levels." (PMID 26934326, 2016). "Gironella and colleagues observed that miR-155 is responsible for repressing TP53INP1 expression and that the restoration of TP53INP1 levels is in accordance with the regression of tumorigenic features of pancreatic cancer." (PMID 27187371, 2016). "TP53INP1 induces cell cycle arrest and apoptosis, and its expression is lost in early stages of pancreatic cancer." (PMID 27187371, 2016). "The current study identified a novel ZIP4-CREB-miR-373 signalling axis that promotes pancreatic cancer growth, through silencing on key tumour suppressor molecules including TP53INP1, LATS2 and CD44." (PMID 23857777, 2013). "Further experimentation indicate that silencing the miR-373 activator, CREB, in pancreatic cancer cells also leads to increased expression of TP53INP1 and CD44, respectively." (PMID 23857777, 2013). "We used TP53INP1, a pro-apoptotic tumour suppressor protein reported to be repressed by miR-155 in pancreatic tumours, as a positive control." (PMID 23637592, 2013). "TP53INP1 transcriptionally blocks SPARC gene expression, and silencing of TP53INP1 increases cell migration in mouse embryonic fibroblasts and pancreatic cancer cells." (PMID 23717325, 2013). "TP53INP1's expression is reduced during the development of breast cancer, gastric cancer, pancreatic cancer and melanoma, but curiously increased in thyroid cancer." (PMID 19014483, 2008). "In pancreatic cancer, TP53INP1 is repressed by miR-155, and its restoration inhibits tumor development." (PMID 19014483, 2008). "TP53INP1 is downregulated during tumorigenesis in most cancers, including pancreatic cancer, gastric carcinoma, hepatocellular carcinoma, and melanoma, suggesting that it may play a role in tumor suppression and cell death." (PMID 31281592, 2019).